CTSG (cathepsin G)
Diseases named in the same sentence as CTSG in open-access papers (continued):
Sharing a sentence is not in itself a finding about the gene and the disease.
tumor (98 papers, 2009 to 2025). "In HCC, NET-associated cathepsin G notably enhances tumor cell invasion and metastatic potential by downregulating E-cadherin level." (PMID 41303697, 2025). "Activated neutrophils secrete Cathepsin G, which is a serine protease and is closely associated with tumor diseases." (PMID 38590662, 2024). "We analyzed the level of CTSG genes in tumor immune microenvironment-associated cells, utilizing the TISCH database." (PMID 37588994, 2023). "A recent study found that the neutrophil-associated serine protease Cathepsin G can enhance the cell adhesion of E-cadherin by activating insulin-like growth factor 1, facilitating tumor cell aggregation, and aiding tumor cells in penetrating blood vessels." (PMID 37359527, 2023). "CTSG is also highly expressed in various cancer types and is associated with tumor angiogenesis and metastasis." (PMID 34361002, 2021). "In patients with hepatocellular carcinoma, NETs-associated cathepsin G induces tumor cell invasion." (PMID 37958788, 2023). "Furthermore, we established a xenograft tumor growth model to investigate the MK2206 effect on CTSG deficiency on tumorigenesis in vivo." (PMID 37151875, 2023). "Few studies have shown that CTSG genes were associated with tumor progression and prognosis." (PMID 37588994, 2023). "NET components MMP9, cathepsin G and neutrophil elastase are all known to contribute to extracellular matrix remodeling as well as provide signals for tumor cell proliferation, migration and tumor-associated angiogenesis." (PMID 30356678, 2018). "However, the detailed mechanism underlying CTSG's anti-tumor function remains less studied." (PMID 41040318, 2025). "On one hand, with MMP-9, cathepsin G, and neutrophil elastase (NE), NETs could induce tumors via promoting tumor distant site spread, shielding immune cell infiltration, killing immune cells, and provoking tumor angiogenesis and cancer-associated thrombosis." (PMID 40868150, 2025). "CDK1 stood out as a candidate target to relieve CTSG's tumor-killing function in the pooled genome-wide CRISPR/Cas9 screening." (PMID 41040318, 2025). "Vice versa, neutrophils can directly attack tumor cells secreting reactive oxygen species (ROS), elastase, or cathepsin G, which can induce apoptosis in cancer cells and limit tumor growth." (PMID 39256468, 2024). "Pro-tumor factors that cause immunosuppression in the tumor microenvironment, such as CCL2, CCL5, neutrophil elastase (NE), and cathepsin G (CG), are expressed more often in N2 neutrophils, along with a greater expression of arginase." (PMID 39090094, 2024). "We observed that CTSG expression in NSCLC is lower compared to adjacent non-tumor tissues and correlates with NSCLC clinical stage." (PMID 39080685, 2024). "Our findings identify that CTSG has a tumor-inhibiting effect on CRC cells via controlling the activity of the Akt/mTOR/Bcl2 mediated anti-apoptotic signaling pathway." (PMID 37151875, 2023). "Consistent with the clinical significance, our data demonstrated that CTSG over-expression markedly suppressed viability and promoted apoptosis of CRC in vitro and vivo, tumor growth was induced, and apoptosis was suppressed after CTSG knockdown." (PMID 37151875, 2023). "N1 subtype secretes CCL3, CCL9, CXCL10, TNF-α, IL12, Cathepsin G, and neutrophil elastase (NE) to recruit, activate and induce proliferation of T-cells to implement anti-tumor influence and improve adaptive immune responses." (PMID 37376417, 2023). "Downregulation of CTSG in HNSC was significantly associated with the primary therapy outcome (p = 0.003), race (p = 0.044), anatomic neoplasm subdivision (p = 0.005), and overall survival (p = 0.015)." (PMID 37588994, 2023). "Our findings suggested that CTSG was an independent prognostic biomarker in HNSC patients and was associated with tumor immune cell infiltration in patients." (PMID 37588994, 2023).
tumor (continued). "Our findings imply that CTSG plays a significant role in promoting tumor progression by facilitating communication between tumor cells and their inflammatory microenvironment." (PMID 37588994, 2023). "The results indicated that CTSG overexpression inhibits tumor growth, and tumors with CTSG overexpression have lower weight and smaller sizes than the control group." (PMID 37151875, 2023). "Granular cytoplasmic positivity for cathepsin G in neutrophils was localised to the tumour surface, microabscesses, or histological ulceration." (PMID 37118737, 2023). "Our results also suggest CTSG would play as a tumor inhibitor gene in CRC, which is consistent with those studies." (PMID 37151875, 2023). "After multivariate analysis, CTSG expression, phase, site, and size of the tumor all remained significant, and these four variables were included in the nomogram model." (PMID 37151875, 2023). "Since Akt/mTOR signaling stimulation supports tumor development by regulating cell growth 33, we examined the functional consequence of CTSG absence-mediated activation of Akt/mTOR action." (PMID 37151875, 2023). "In animal models of breast cancer, cathepsin G potentiates tumor aggregation in vasculature and form distal tumor emboli." (PMID 37958788, 2023). "Tumor-derived cathepsin G can induce cell migration and promote the entry of cancer cells into blood vessels." (PMID 37152022, 2023). "All these pieces of evidence further showed that CTSG genes impacted the prognosis of HNSC patients by affecting tumor immune cell infiltration." (PMID 37588994, 2023). "NETs are neutrophil-derived webs of DNA decorated with granular proteins, including NE, matrix metalloproteinase 9, MPO, and cathepsin G, with the ability to promote tumor cell proliferation, angiogenesis, and metastasis." (PMID 35036439, 2022). "Rather, we observed an important role for the interaction of neutrophil surface expressed Cathepsin G with tumor RAGE in promoting neutrophil-mediated cytotoxicity towards the tumor cells." (PMID 35453656, 2022). "Tumor cells expressing RAGE on their cell surface will be recognized by Cathepsin G expressed on the neutrophils." (PMID 35453656, 2022). "Among the 7 enrolled immune-related genes, Cathepsin G is a neutrophil serine protease and its interaction with receptor for advanced glycation end products can trigger neutrophil cytotoxicity to kill tumor cells." (PMID 35725413, 2022). "We have recently shown that Cathepsin G expressed on the neutrophil surface interacts with tumor RAGE, and this interaction facilitates neutrophil cytotoxicity." (PMID 35453656, 2022). "Last, the mechanisms of neutrophil recognition of cancer cell will be highlighted with a specific emphasize on the newly recognized interaction between neutrophil-surface-expressed Cathepsin G with tumor cell expressed RAGE." (PMID 34572138, 2021). "The comparison of gene expressions in tumor and normal tissues revealed that CTSG and LCORL were downregulated, while TNFRSF4 and PLAU were upregulated in OSCC tissues." (PMID 34497859, 2021). "Except from their established role in host-pathogen interactions, NETs modulate cancer-associated procoagulant activity and promote tumor growth by including tumor-promoting components such as MMP-9, cathepsin G and neutrophil elastase." (PMID 33363012, 2020). "More recently, an interaction between the receptor for advanced glycation end products (RAGE), which is expressed on tumor cells, and cathepsin G present on murine neutrophils was shown to mediate in vitro tumor cell cytotoxicity in a H2O2-dependent manner." (PMID 32849639, 2020). "The interaction of neutrophil Cathepsin G with tumor cell RAGE is required for neutrophil cytotoxicity to kill tumor cell, while neutrophil proteinase 3 interacts with tumor cell RAGE to promote the bone metastasis of prostate cancer." (PMID 33101283, 2020).
tumor (continued). "Cathepsin G released from N2 TANs promoted angiogenesis and migration of tumor cells through upregulating vascular endothelial growth factor (VEGF) and enhancing TGF-β signaling." (PMID 29930287, 2018). "Only one gene, CTSG is common between male and female specific biomarkers that points to the different regulation of tumor microenvironment in different genders." (PMID 28349958, 2017). "Serine proteases, such as elastase and cathepsin G, secreted by TANs, can degrade the basement membrane and promote tumor cell invasion through the basement membrane." (PMID 28077792, 2017). "Cathepsins B and D were localized to CSCs within the tumor nests, while cathepsin B was localized to the CSCs within the peri-tumoral stroma, and cathepsin G was localized to the tryptase+ phenotypic mast cells within the peri-tumoral stroma." (PMID 28775982, 2017). "Other pro-tumorigenic functions of TAN have been reported, such as tumor cell invasion via secretion of elastases, MMP8, MMP9 and cathepsin G and tumor cell proliferation via COX-2-dependent prostaglandin E2 synthesis." (PMID 27259252, 2016). "Blocking cathepsin G and cathepsin K significantly reduces tumor-induced osteolysis, which suggests that cathepsin K and cathepsin G are crucial in the microenvironment of cancer-induced osteolytic lesions." (PMID 26440411, 2015). "First cathepsin G binds to the tumor cell surface, independently of its catalytic site, and then induces cell aggregation, which is dependent on its enzymatic activity." (PMID 26819959, 2015). "Cathepsin G secreted by neutrophils infiltrating intratumor environments is a candidate factor that influences the metastatic capacity of tumor cells." (PMID 24803743, 2014). "One possibility is that cathepsin G alters the character of adherence by cleaving the integrins of tumor cells." (PMID 24803743, 2014). "Our findings provide the first evidence that cathepsin G regulates E-cadherin function, suggesting that cathepsin G has a novel modulatory role against tumor cell-cell adhesion." (PMID 19920860, 2009). "The in vivo effect of cathepsin G is thus an important subject of future study to learn the role of tumor-infiltrating neutrophils." (PMID 19920860, 2009). "Cathepsin G has been shown to facilitate tumor aggregate formation in human breast cancer cells." (PMID 40391215, 2025). "In HCC models, the in vivo effectiveness of cathepsin G inhibition was less pronounced than in vitro, suggesting that compensatory pathways or the tumor microenvironment may limit the clinical impact of cathepsin G-targeted approaches." (PMID 41303697, 2025). "Interestingly, studies on colorectal cancer (CRC) have shown that the expression of cathepsin G was inhibited as the tumor developed." (PMID 41303697, 2025). "It has been shown that cathepsin G can also facilitate angiogenesis and tumor cell migration." (PMID 40391215, 2025). "Furthermore, cathepsin G can enhance the adhesion and migration of cancer cells, as well as facilitate tumor formation by regulating tumor-matrix interactions." (PMID 38590662, 2024). "Similarly, MC0 (Cathepsin G+Tryptase+) decreased from distal normal tissues to the tumor-normal interface to the tumor core, whereas the reverse was true for MC4 (VEGFA+Tryptase+)." (PMID 39840068, 2024). "Whether for LUAD or LUSC, the expression of CTSG in normal tissues was significantly higher than that in tumor tissues of different clinical stages (P < 0.05), and in clinical stages 1, 2, and 3, the more advanced the stage, the lower the expression of CTSG." (PMID 39080685, 2024). "To test if CTSG plays a critical role in the tumor inhibitory effect of the combination of CB-839 and 5-FU mediated by NETs in vivo, we treated HCT116 xenograft tumors established subcutaneously in nude mice with vehicle control or the drug combination with or without CTSGi." (PMID 38194275, 2024).
tumor (continued). "In addition, it can inhibit the activation of CD + T cells and increase the secretion of cathepsin G, neutrophil elastase, and other factors that promote tumor metastasis." (PMID 37251954, 2023). "Altogether, these outcomes demonstrate that CTSG may act as a tumor suppressor gene via Akt/mTOR/Bcl2-mediated anti-apoptotic signaling inactivation, and CTSG represents a potential therapeutic target in CRC." (PMID 37151875, 2023). "CTSG expression correlated with tumor size, location, and TNM stage." (PMID 37151875, 2023). "Interestingly, we found that patients with increased CTSG expression had more favorable medical results than individuals with reduced CTSG expression and CTSG related to tumor size, location, and pathological stages in CRC." (PMID 37151875, 2023). "Additionally, neutrophils promote tumor motility, migration and invasion via the release of neutrophil elastase, cathepsin G, proteinase 3, MMP8 and MMP9." (PMID 35682709, 2022). "Inflammatory proteases from neutrophils (proteinase 3, elastase, and cathepsin G) and mast cells within the tumor microenvironment (chymase, tryptase, and granzyme B) can process full-length IL-33 into shorter mature forms (18–21 kDa), with a 10- to 30-fold higher amount of activity." (PMID 35409061, 2022). "Importantly, Cathepsin G knockout neutrophils exhibited impaired tumor cytotoxicity toward RAGE-proficient tumor cells, and RAGE knockout tumor cells showed limited susceptibility to neutrophil cytotoxicity." (PMID 35453656, 2022). "It remains unclear that the detailed function of Cathepsin G in tumor immune response and its prognostic value for BCa patients." (PMID 35725413, 2022). "Interestingly, SCC antigen, a serological marker of SCC tumor advancement, has been demonstrated to inhibit chymase and cathepsin G, another bypass of the RAS." (PMID 33513805, 2021). "The eight-gene-signature prognostic model (ANGPTL5, CD1B, CD1E, CNTFR, CTSG, EDN3, IL12B, and IL2)-based high- and low-risk groups were significantly related to overall survival (OS), tumor microenvironment (TME) immune cells, and clinical characteristics in LUAD." (PMID 34745015, 2021). "Also, Cathepsin G has been reported to induce tumor cell aggregation which is beneficial for metastasis formation." (PMID 29330531, 2018). "Cathepsin G has important role in tumor development and metastasis." (PMID 29290980, 2017). "Cathepsin G may act on E-cadherin-positive tumor cells to induce detachment from the ECM to facilitate the dissemination of tumor cell aggregates." (PMID 24803743, 2014). "In addition to MCF-7 cells, a comparison to other proteases of the effect of cathepsin G on the motility of other tumor cells, including highly metastatic MDA MB-231 cells, should be further examined." (PMID 24803743, 2014). "Further studies are needed to identify the binding molecule(s) of cathepsin G in cells to elucidate the mechanism underlining this nonoverlapping activity of cathepsin G-induced alterations in the adherence capacity of tumor cells." (PMID 24803743, 2014). "It is reported that cathepsin G is up regulated through tumor stromal interactions and activates Pro-MMP9, active MMP9 cleaves and releases active TGF-beta, and active TGF-beta can then promote tumor growth and enhance osteoclast activation and subsequent bone resorption." (PMID 21859454, 2011). "However, the regulatory role of neutrophil proteases including cathepsin G in tumor progression and metastasis is not fully understood." (PMID 19920860, 2009). "In these cases, cathepsin G-induced tumor cell adhesion via E-cadherin may exert deleterious effects on tumor development and metastasis." (PMID 19920860, 2009). "The understanding of the reactions involved in the induction of cell-cell adhesion by cathepsin G might provide novel insights into tumor growth and metastasis." (PMID 19920860, 2009).
tumor (continued). "We postulate that cathepsin G secreted by infiltrated neutrophils in tumor tissue may have a novel modulatory role in tumor development." (PMID 19920860, 2009). "Our data revealed that CTSG could be a critical tumor suppressor in CRC." (PMID 37151875, 2023). "A prognostic index for tumor samples could be calculated by the formula: IRGPI = (HTN3 expression * 0.096) + (CTSG expression * −0.152) + (MAPT expression * 0.122) + (CCL28 expression * −0.094) + (PTX3 expression * 0.138) + (SEMA3G expression * −0.140) + (USP2 expression * 0.107)." (PMID 36845378, 2023). "Our results showed that CTSG down-regulated expression effects on tumor growth might be reversed, and Akt phosphorylation level and its downstream substrate mTOR decreased after using MK2206, indicating that CTSG may suppress CRC growth through Akt/mTOR signaling pathway." (PMID 37151875, 2023). "The lack of CTSG expression by CA tumor cells may relate to the finding that it reduces the risk of metastasis by increasing cell-cell adhesion." (PMID 34428252, 2021). "Moreover, cathepsin G promotes tumor cell-cell adhesion and migration in cancer cells." (PMID 29290980, 2017). "Also, cathepsin G can promote angiogenesis and tumor cell migration." (PMID 26819959, 2015). "In contrast, cathepsin G-caused suppression of the adhesion capacity between highly metastatic E-cadherin-negative tumor cells and the ECM may inhibit metastasis." (PMID 24803743, 2014). "The drug combination increases ROS in neutrophils, triggering NET formation (NETosis) and the release of cathepsin G (CTSG), which enters tumor cells via RAGE, cleaves 14-3-3ε, and activates BAX-dependent mitochondrial apoptosis." (PMID 40805288, 2025). "Previous studies have demonstrated that neutrophils release neutrophil elastase (NE), cathepsin G (CG) and matrix metalloproteinases 9 (MMP9) to remodel the ECM, ultimately leading to tumor growth and metastasis." (PMID 40963631, 2025). "In terms of upregulated DEGs, seven genes (ABI3BP, CTSG, DPP4, CCL18, OSR2, GRIA3, MMP2) demonstrated reduced expression in tumor compared to normal tissue." (PMID 39062832, 2024). "CTSG also mediates the direct tumor killing by neutrophils through the receptor for advanced glycation end products (RAGE), though RAGE-CTSG inhibition still allows partial cytotoxic effects, suggesting other synergistic components." (PMID 39736788, 2024). "(D) Heatmaps showing expression of ICAM1 and ICAM-1 cleavage related proteases MMP9, ELANE, CTSG, ADAM10, and ADAM17 in normal or tumor tissue of 22 different cancer types." (PMID 37732732, 2023). "The majority of PRGs were significantly elevated in tumor tissue, while GSDMA and CTSG were significantly decreased." (PMID 37221570, 2023). "Both CEACAM6 and CTSG were downregulated in this study, which indicated the importance of CEACAM6 and CTSG in tumor recurrence in HCC patients after LT." (PMID 37089051, 2023). "They potentially facilitate tumor progression by the release of NE, cathepsin G, and MMP9, as well as tumor metastasis." (PMID 36031601, 2022). "We recently observed that Cathepsin G expressed on the neutrophil surface interacts with tumor RAGE, and this interaction is important for forming the neutrophil–tumor cell synapse required for tumor cell killing." (PMID 35453656, 2022). "Neutrophils elastase (NE) and cathepsin G (CG) awaken dormant cancer cells by cleaving the extracellular matrix (ECM) protein lamin, generating an epitope that binds to tumor integrins, leading to the proliferation and migration of cancer cells." (PMID 35203640, 2022). "On the other hand, the anti-tumor function of neutrophils was found to rely on the interaction between tumor-surface-expressed receptor for advanced glycation end products (RAGE) and Cathepsin G expressed on the neutrophil surface." (PMID 34572138, 2021).